FEM1A (fem-1 homolog A)
Description:
Substrate-recognition component of a Cul2-RING (CRL2) E3 ubiquitin-protein ligase complex of the DesCEND (destruction via C-end degrons) pathway, which recognizes a C-degron located at the extreme C terminus of target proteins, leading to their ubiquitination and degradation. The C-degron recognized by the DesCEND pathway is usually a motif of less than ten residues and can be present in full-length proteins, truncated proteins or proteolytically cleaved forms. The CRL2(FEM1A) complex specifically recognizes proteins with an arginine at the C-terminus: recognizes and binds proteins ending with -Lys/Arg-Xaa-Arg and -Lys/Arg-Xaa-Xaa-Arg C-degrons, such as SIL1 or OR51B2, leading to their ubiquitination and degradation. Promotes ubiquitination and degradation of SLBP. Involved in PGE2-EP4-mediated inhibition of inflammation of macrophages via interaction with NFKB1 and PTGER4 (By similarity). Promotes inflammation in brain microglia through MAP2K4/MKK4-mediated signaling (By similarity).
Synonyms: EPRAP
Tractability: PROTAC: ubiquitination databases record sites on it.
Gene: Protein-coding gene on chromosome 19 (4,791,734 to 4,801,273, forward strand). Ensembl gene ENSG00000141965.
Subcellular location: Mitochondrion; Cytoplasm
Subcellular location (Human Protein Atlas): Golgi apparatus; Nucleoplasm; Cytosol
Pathways (Reactome):
Metabolism of proteins: Neddylation
Gene Ontology:
Molecular function: EP4 subtype prostaglandin E2 receptor binding; molecular adaptor activity; protein binding; ubiquitin-like ligase-substrate adaptor activity
Biological process: negative regulation of inflammatory response; ubiquitin-dependent protein catabolic process via the C-end degron rule pathway; positive regulation of inflammatory response; proteasome-mediated ubiquitin-dependent protein catabolic process; protein ubiquitination; regulation of inflammatory response
Cellular component: Cul2-RING ubiquitin ligase complex; cytoplasm; Golgi apparatus; mitochondrion; nucleoplasm; cytosol; ubiquitin ligase complex
Genetic constraint (gnomAD): Loss-of-function variants: 2 observed, 1.78 expected, observed/expected ratio (o/e) 1.13, 90% interval 0.39 to 1.9. That is too few expected variants to judge how well the gene tolerates losing a copy. Missense variants: 721 observed, 837.47 expected, observed/expected ratio (o/e) 0.86, 90% interval 0.81 to 0.92. Synonymous variants: 391 observed, 386.3 expected, observed/expected ratio (o/e) 1.01, 90% interval 0.93 to 1.1.
Homologues: Orthologues: chimpanzee FEM1A (96% identical), pig FEM1A (94% identical), dog FEM1A (92% identical), guinea pig FEM1A (91% identical), mouse Fem1a (89% identical), rat Fem1a (88% identical), mouse Fem1al (86% identical). Paralogues in human: FEM1C (65% identical), FEM1B (37% identical), ANKRD33B (13% identical), ANKRD33 (12% identical).
Diseases named in the same sentence as FEM1A in open-access papers:
FEM1A is named in the same sentence as 13 diseases in open-access papers, as found by Europe PMC text mining. Sharing a sentence is not in itself a finding about the gene and the disease. The quoted sentences say what the papers report.
myocardial infarction (1 paper, 2021). Gross necrosis of the myocardium, as a result of interruption of the blood supply to the area, as in coronary thrombosis. "FEM1A is localized within mitochondria of cardiac muscle, is increased after myocardial infarction in mice and may regulate apoptosis." (PMID 34768754, 2021).
FEM1A also shares sentences with these, for which no sentence is quoted: cancer (1 paper); colitis (1); colon cancer (1); colonic polyps (1); COVID-19 (1); inflammatory bowel disease (1); intestinal polyp (1); melanoma (1); polycystic ovary syndrome (1); polyp (1); tumor (1); ulcerative colitis (1).